IL1B (interleukin 1 beta)
Diseases named in the same sentence as IL1B in open-access papers (continued):
Sharing a sentence is not in itself a finding about the gene and the disease.
inflammation (488 papers, 2009 to 2026). Aberrant reaction of the microcirculation characterized by movement of fluid and leukocytes from the blood into extravascular tissues. "While HDM exposure is known to induce T helper 2 (Th2)-mediated eosinophilic inflammation, its chronic effects on interleukin-1β (IL-1β)-associated neutrophilic inflammation remain poorly understood." (PMID 41445736, 2025). "According to previous reports, inflammatory cytokines such as TNF-α, IL-1β, and IL-6 are closely associated with the occurrence of intestinal inflammation." (PMID 38892496, 2024). "This process leads to the release of pro-inflammatory cytokines (TNF-α, IL-1β, IL-6), which are implicated in airway inflammation." (PMID 39000242, 2024). "The TLR4/NLRP3 pathway is critical in the pathogenesis of ALI, causing sustained production of cellular factors such as IL‐1β and IL‐18, which ultimately leads to a massive outbreak of lung inflammation, resulting in tissue injury and even ARDS." (PMID 39139945, 2024). "Aside from precise regulation by caspase-1, pathogenic bacterial enzymes such as SpeB and LasB directly cleaves Pro-IL-1β in a bioactive IL-1β that can cause host inflammation-related diseases." (PMID 39038050, 2024). "In summary, the results reveal a critical effect of IL-1β signaling in vascular inflammation, senescence and TAA formation with Sirt6 deficiency." (PMID 37394473, 2023). "Noteworthy, FOXO3 transcription factor was found to associate with chronic periapical inflammation in periapical lesion specimens via IL-1β release regulation." (PMID 35955417, 2022). "To address the possibility that the chronic nasal inflammation caused systemic inflammation, we examined the expression levels of representative pro-inflammatory cytokines, TNFα and IL-1β, using serum and spleen extraction by ELISA analysis." (PMID 33633180, 2021). "The presence of IL1β was associated with caseous granulomatous inflammation during M. tuberculosis, while blocking IL1β production relieved pulmonary inflammation." (PMID 34502407, 2021). "Among them, those associated with systemic inflammation have been characterized and shown to express high levels of classical pro-inflammatory genes including Il6, Cxcl10, Il1b and Tnf." (PMID 34483912, 2021). "Caspase‐1 NLRP3 and ASC are components of NLRP3 inflammasomes that can cause cardiac inflammation and cardiac dysfunction via IL‐1β and TGF‐β1 release." (PMID 33270361, 2021). "SARS-CoV-2 recognition by Toll Like Receptor (TLR) causes the production of IL-1β, which mediates lung inflammation, fever, and fibrosis." (PMID 33147850, 2020). "For example, the binding of SARS-CoV-2 to the TLR causes the release of pro-IL-1β, which is cleaved by caspase-1, followed by inflammasome activation and production of active mature IL-1β, which is a mediator of lung inflammation, fever, and fibrosis." (PMID 32438620, 2020). "Only four strains induced the inflammatory cytokines TNF-α, IL-12(p70), IL-6 and IL-1β, while the remaining Lactobacillus strains downregulated these, which is again reassuring as genital inflammation has been linked to HIV and STI risk." (PMID 32497109, 2020). "NLRP3 inflammasome-dependent, IL-1β-mediated IL-17 responses have been associated with neutrophilic airway inflammation and AHR." (PMID 32423405, 2020). "Taken together, these evidences suggest that toll-like receptor 4 activation and subsequent upregulation of IL-1RI likely play an important role in ectopic orofacial pain associated with IL-1β expression in macrophages following tooth pulp inflammation." (PMID 33081813, 2020). "Chronic inflammation is associated with ageing and characterized by the increased production of pro-inflammatrory mediators such as IL-1β, TNF-α and IL-8 and the activation of NF-кB signaling, as well as infiltration of inflammatory cells." (PMID 30154427, 2018). "The present work demonstrates the important role of IL-1β in acute lung inflammation and suggests a potential underlying mechanism." (PMID 28276511, 2017).
inflammation (continued). "Liver inflammation has been shown to be associated with elevated production of various cytokines such as IL-1β, TNF-α and IFN-γ, which have been implicated in hepatocarcinogenesis." (PMID 28638434, 2017). "IL-1β inhibition, as demonstrated in the CANTOS trial, has shown significant reductions in cardiovascular events in high-risk patients, suggesting that IL-1β blockade could also be beneficial in trauma patients with persistent myocardial inflammation." (PMID 40710793, 2025). "Consistent with previous mouse studies, genes associated with epidermal inflammation (e.g., IL-6, IL1B, S100A7, S100A8, and S100A9) and matrix metalloproteases (MMPs) were also significantly upregulated, as were E- and L-selectin, which are required for leukocyte entry into skin." (PMID 41150413, 2025). "Chronic inflammation may also be derived in part from senescent cells, and elevated IL-1β and IL-6 are associated with age-related disease." (PMID 35111375, 2022). "In addition, the in vitro effects of C. phaeocaulis translate into a decrease in IL-1β levels and inflammatory cell infiltration in an animal model of airway inflammation caused by nanoparticles." (PMID 35408502, 2022). "Our findings may provide novel insight into the detailed mechanisms underlying the NLRP3 inflammasome and IL-1β synthesis observed in severe neutrophilic asthmatic airway inflammation." (PMID 34064821, 2021). "The pro-inflammatory cytokines: namely TNF-α and IL-1β, and anti-inflammatory IL-10 are associated with lung inflammation and function, and studies using rodent models found an attenuation of both acute and chronic lung inflammation by polyphenol and anthocyanin intake." (PMID 34959825, 2021). "Furthermore, the levels of major inflammatory cytokines (TNF-α, IL-6, and IL-1β) associated with hepatic inflammation were also significantly lower." (PMID 34204055, 2021). "IL‐1β has been associated with the presence of joint inflammation and cartilage destruction." (PMID 30311192, 2019). "Therefore, we studied local mRNA levels of additional cytokines that have been associated with ILC3 homeostasis, such as CXCL6, IL-1β, IL-12, IL-18, and IL-23 and/ or intestinal inflammation, including IL-1β, TGF-β, IFN-γ, and TNF-α." (PMID 28505204, 2017). "Furthermore, our studies demonstrate that proteases in poultry dust induce, in addition to IL-8 and IL-6, other genes implicated in lung inflammation such as IL-1β, CCL2, ICAM-1, PTGS2 and TLR4 in alveolar as well as bronchiolar epithelial cells." (PMID 27770804, 2016). "This extract, orally administered at 25, 50, or 100 mg/kg at 96, 72, 48, 24, and 2 h before intestinal inflammation induction, showed anti-inflammatory effects associated with increased IL-10 synthesis, reduced oxidative stress, and reduction in the pro-inflammatory cytokines IL-1β, IL-6, and TNF-α." (PMID 37242733, 2023). "Many studies have demonstrated that colonic inflammation is associated with decreased concentrations of SCFAs in the colon, resulting in decreased expression of intestinal tight junction proteins and higher expression of proinflammatory factors such as IL-1β and IL-6." (PMID 35935130, 2022). "Disruption of this barrier is a hallmark of chronic intestinal inflammation particularly in IBDs, and is primarily driven by pro-inflammatory cytokines, such as TNF-α, IFN-γ, IL-1β, and IL-6." (PMID 42278255, 2026). "Previous research has shown that individuals with frailty exhibit elevated levels of inflammatory markers such as C-reactive protein (CRP), interleukin-1 beta (IL-1β), and IL-6, accompanied by chronic systemic inflammation and increased monocyte counts." (PMID 40697920, 2025). "The presence of low‐grade intestinal inflammation was further confirmed by an increase in mRNA levels of intestinal inflammatory cytokines, namely Tnf‐α, Il‐1β, and Il‐6, which were analyzed in whole gut tissue samples from the small intestine and colon." (PMID 40051115, 2025).
inflammation (continued). "KC-mediated hepatic inflammation, most notably IL-1β, led to the transcriptional inhibition of A1AT by HNF4α." (PMID 39939782, 2025). "This inflammasome plays a crucial role in processing and releasing IL-1β, a potent pro-inflammatory cytokine that exacerbates liver inflammation and worsens the injury." (PMID 40620672, 2025). "Previous studies have suggested a significant role of pro-inflammatory cytokines, such as IL-1β and IL-18, in liver inflammation and damage." (PMID 40379874, 2025). "Studies suggest that in HI and WMI models, microglia trigger severe brain inflammation via caspase-1-dependent pyroptosis, releasing IL-1β and IL-18, which impair OPC differentiation and maturation." (PMID 40254577, 2025). "In the present study, TiO2 NPs up-regulated mRNA expression of TNF-α and IL-1β in both liver and kidney suggesting its ability to induce hepatic and renal inflammation." (PMID 40447623, 2025). "In contrast, an increase of IL1B, a proinflammatory cytokine also involved in modulation of autoimmune inflammation, was observed in the young plasmas." (PMID 41573543, 2025). "TLR4 activation leads to increased expression of inflammatory genes such as NF-κB, Myd88, and CD14, resulting in the production of inflammatory cytokines (IL-1β, IL-6, TNF-α), which cause liver inflammation and damage." (PMID 40362886, 2025). "Analysis of IL-1β expression changes in synovial tissue throughout the course of the disease shows that synovial inflammation develops fastest in the early stages of the disease, which is the main development stage of synovial inflammation." (PMID 40919498, 2025). "HH also caused cardiac inflammation and fibrosis, especially in the OVX + HH group, which had elevated proinflammatory cytokines (IL-1β, IL-6, TNF-α) and decreased anti-inflammatory cytokines (TGF-β, IL-10)." (PMID 40108505, 2025). "IL-1α and IL-1β, acting through the IL-1 receptor (IL-1R), further propagate pericardial inflammation, with IL-1α serving as an early alarmin and IL-1β enhancing the immune response." (PMID 41136179, 2025). "Recent studies have indicated that GO can significantly diminish the production of the proinflammatory cytokines TNF-α, IL-1β, and IL-6 in LPS-induced macrophages or murine models, thereby reducing airway inflammation." (PMID 41562115, 2025). "To further understand the role of inflammatory cytokines in AHL‐related cochlear inflammation, we used real‐time PCR to assess the expression of three key cytokines, IL‐6, IL‐1β, and TNF‐α, in the cochlea." (PMID 39148148, 2024). "PMOP is strongly associated with systemic chronic inflammation, which is often accompanied by the augmentation of pro-osteoclastogenic factors such as TNF-α and IL-1β." (PMID 38542877, 2024). "Previous studies have indicated that airway inflammation can lead to the release of pro-inflammatory cytokines such as IL-1β, IL-6 and TNF-α by the human broncho-epithelial cells and macrophages." (PMID 37851060, 2024). "LPS induced lung inflammation, as evidenced by increased IL-1β, IL-6 and TNF-α levels in the serum compared to those in the Sham group." (PMID 38802896, 2024). "To determine the effect of inhibiting CD44-ICD on the release of inflammatory mediators in LPS-induced hepatic inflammation in mice and Chang cells, we assessed the level of hepatic IL-1β, NO, and INOS in mice and the level of IL-1β in Chang cells." (PMID 39201593, 2024). "Activated macrophages infiltrate RA patients’ synovial fluid and secrete pro-inflammatory cytokines (TNF-α, IL-1β, and IL-6), which in turn promote synovial inflammation and lead to cartilage and bone destruction, which correlates with the severity of RA." (PMID 38966637, 2024). "Previous studies have found that stem cells can produce immunomodulatory cytokines such as IL-10 to inhibit proinflammatory cytokine secretions such as TNF-α and IL-1β, thereby alleviating pulmonary inflammation." (PMID 39011319, 2024).
inflammation (continued). "Elevated IL-1β and IL-18 production by NLRP3 inflammasome-mediated pyroptosis of human primary trophoblasts has been implicated in the induction of placental inflammation and PE syndrome." (PMID 36829486, 2023). "In conclusion, elevated Arg‐II in the lung promotes age‐related pulmonary inflammation and fibrosis in the cell autonomous and paracrine manner involving interaction between epithelial cells and fibroblasts, whereby IL‐1β and TGF‐β1 play a crucial role." (PMID 36794355, 2023). "Studies on animal models have also shown that brain inflammation is inhibited in animals that have received FA due to the reductions in the expression of pro-inflammatory cytokines IL-6, IL-1β, and TNF-α." (PMID 37590236, 2023). "For instance, the effect of butyrate to protect against gut inflammation has been proven to be dependent on the inhibition of HDACs in macrophages and dendritic cells to down-regulate pro-inflammatory cytokines, e.g., IL-1b, IL-6 and IL-8." (PMID 37110213, 2023). "The administration of the caspase-1 inhibitor z-YVAD-fmk or caspase-1 in mice suppresses BLM-induced IL-1β production, lung inflammation, and fibrosis." (PMID 36834561, 2023). "IL-1β, a proinflammatory cytokine released by various immune modulating cells, is related to intestinal inflammation." (PMID 36872332, 2023). "In this study, Duan's research suggested that Pb exposure will cause the occurrence of intestinal inflammation in fish, which was confirmed by the mRNA expression changes in immune-related genes (TNF-α, IL-1β, IL-8, and IL-10)." (PMID 37731918, 2023). "Both SiO2 and TiO2 nanoparticles have been reported to trigger IL-1β secretion in the lung and provoke airway inflammation in animals." (PMID 35408502, 2022). "Oxidative stress causes liver inflammation, leading to secretion of pro-inflammatory cytokines such as TNF-α, interleukin-1 beta (IL-1β) and interleukin-6 (IL-6)." (PMID 36358518, 2022). "NLRP3 inflammasome-dependent IL-1β production also acts as a major chemoattractant of neutrophils and contributes to the development of neutrophilic airway inflammation." (PMID 36428547, 2022). "It has been reported that the occurrence of cognitive disturbances upon CNS inflammation has been correlated with increased levels of IL-6 and IL-1β." (PMID 35255943, 2022). "The levels of TNF-α, IL-6, and IL-1β in the EtOH group were remarkably higher than that in the Ctrl group (p < 0.001), indicating the occurrence of liver inflammation." (PMID 35681289, 2022). "Pro-inflammatory cytokines, TNF-α, and IL-1β, which are produced during intestinal inflammation have important intestinal epithelial tight junction barrier-modulating actions, highly related to inflammatory diseases of the gut." (PMID 35958130, 2022). "Aberrant and excessive activation of some cytokines is involved in the pathogenesis of IBD, among which IL-1β and IL-6 have been regarded to play a prominent role in the initiation and maintenance of colonic inflammation, respectively." (PMID 35330829, 2022). "We previously reported the mediating roles of BLT2 in regulating the production of IL-17 and NLRP3-dependent IL-1β in neutrophilic airway inflammation." (PMID 36428547, 2022). "Prolonged P. aeruginosa infections have been linked to chronic inflammation in the CF lung, whose hallmarks are increased levels of cytokines (i.e., TNF-α, IL-1β, IL-6) and neutrophil attraction by chemokines, like IL-8." (PMID 35903151, 2022). "IL-1β is an important inflammatory cytokine secreted by macrophages, which can participate in the occurrence of chronic pelvic inflammation by inducing pro-inflammatory cytokines to accumulate in endothelial cells." (PMID 36474249, 2022). "Consistent, treatment of silica-instilled mice with tetracycline significantly reduced pulmonary caspase-1 activation as well as IL-1β and IL-18 production, thereby ameliorating pulmonary inflammation and lung injury." (PMID 35130879, 2022).
inflammation (continued). "Expression of miR-223 in neutrophils inhibits the NLRP3/IL-1β axis, reduces airway inflammation, and reduces NLRP3 (Nucleotide-binding oligomerization domain, leucine-rich repeat and pyrin domain-containing 3) levels and IL-1β release." (PMID 35634335, 2022). "RS provided also exerted a protective role against DSS-induced colonic inflammation as reflected by a decrease in colonic pro-inflammatory cytokine levels of IL-1β, IL-6, TNF-α, and IFN-γ in proximal or distal segments." (PMID 35836245, 2022). "Liver fat accumulation can promote the release of a variety of pro-inflammatory cytokines, such as tumor necrosis factor-α (TNF-α), interleukin-6 (IL-6), interleukin-1β (IL-1β), leading to liver inflammation and cellular damage." (PMID 35630624, 2022). "T2DM can induce liver inflammation evidenced by an increase of proinflammatory cytokines NF-κB, TNF-α, IL-6, and IL-1β, which is associated with cell apoptosis and oxidative stress, all factor promoting HCC progression." (PMID 35002979, 2021). "The inflammasome activates cleavage of pro-IL-1β by caspase-1 into active IL-1β, which mediates lung inflammation and fibrosis." (PMID 33584343, 2021). "According to published data, a deficit of IL-1α and/or IL-1β is followed by uncontrolled bacilli growth and pulmonary inflammation in mice." (PMID 34442871, 2021). "It is widely known that the transient expression of IL-1β can induce lung inflammation, increase TNF-α, and contribute to progressive tissue fibrosis." (PMID 35095920, 2021). "In contrast, disruption of Smad3 prevented CRP-exacerbated renal inflammation with sparse F4/80+ cell infiltration and attenuated IL-1β and MCP-1 upregulation as seen in CRP Tg/Smad3 KO mice." (PMID 34671208, 2021). "In particular, the proinflammatory cytokine IL-1β plays a critical role in neutrophil recruitment and activation, which contribute to the development of severe neutrophilic airway inflammation in the airways of the lungs." (PMID 34064821, 2021). "As reported in several studies, PM2.5 exposure is known to induce pulmonary inflammation by inducing IL-1β signaling activation, and YG-1 extract was found to reduce this in our study." (PMID 34684415, 2021). "In the present study, kidney dysfunction was characterized by increased serum BUN and inflammatory cytokine IL-1β levels and renal inflammation in hyperuricemic rats." (PMID 34684325, 2021). "This highlights that the IPA/miR-26A/IL-1β cascade is a promising therapeutic strategy for chronic muscle inflammation." (PMID 34830317, 2021). "Our results shown that PE effectively alleviate mammary inflammation by inhibiting the expression and secretion of IL-6, IL-1β, TNF-α in vivo and in vitro, and inhibiting the synthesis of iNOS and MPO." (PMID 34383710, 2021). "SARS-CoV-2 can trigger endothelial inflammation and the production and release of inflammatory cytokines such as IL-1β, TNFα, and IL-6." (PMID 34792686, 2021). "P2X4R mediates allergen-induced airway inflammation through the regulation of priming dendritic cells for T helper 2 (Th2), inducing IL-1ß (Interleukin 1 beta) secretion." (PMID 33986747, 2021). "Previous studies have shown that LIPUS can ameliorate synovial inflammation in a destabilization of the medial meniscus (DMM) mouse model by inhibiting the production of mature IL1B/IL-1β and reducing the number of infiltrating inflammatory cells." (PMID 32462002, 2020). "More importantly, we investigated the role of LRNA9884 in IL-1β driven renal inflammation via siRNA-mediated silencing (siLRNA9884) in mTECs in vitro." (PMID 33192605, 2020). "Systemic vascular inflammation increases with ageing and release of several pro-inflammatory mediators such as IL -1, IL - 6, IL-1β, IFNs and several other mediators." (PMID 33132762, 2020). "Previous studies have shown that SiONPs exposure increases the production of TNF-α, IL-6, and IL-1β and elevates inflammatory cell recruitment into lung tissues, resulting in the aggravation of airway inflammation." (PMID 32164364, 2020).